RHOJ (ras homolog family member J)
Description:
Plasma membrane-associated small GTPase specifically involved in angiogenesis. Required for endothelial cell migration during vascular development via its interaction with GLUL. Elicits the formation of F-actin-rich structures, thereby regulating endothelial cell migration.
Synonyms: ARHJ; RASL7B; TCL; FLJ14445; TC10B
Tractability: Antibody: UniProt places it where antibodies can reach, with high confidence; its Gene Ontology location is reachable by antibodies, with high confidence; the Human Protein Atlas places it where antibodies can reach.
Gene: Protein-coding gene on chromosome 14 (63,204,114 to 63,293,508, forward strand). Ensembl gene ENSG00000126785.
Subcellular location: Cell membrane
Subcellular location (Human Protein Atlas): Plasma membrane; Nucleoli; Nucleoplasm
Pathways (Reactome):
Signal Transduction: RHOJ GTPase cycle
Gene Ontology:
Molecular function: GTP binding; GTPase activity; protein binding; protein kinase binding; G protein activity
Biological process: actin cytoskeleton organization; positive regulation of cell migration involved in sprouting angiogenesis; regulation of endothelial cell migration; regulation of sprouting angiogenesis; actin filament organization; endocytosis; establishment of cell polarity; small GTPase-mediated signal transduction
Cellular component: extracellular exosome; plasma membrane
Genetic constraint (gnomAD): Loss-of-function variants: 10 observed, 19.99 expected, observed/expected ratio (o/e) 0.5, 90% interval 0.31 to 0.85. The upper end of that interval is the gene's LOEUF score, 0.85, which puts it in group 3 of 6, group 1 being the genes least tolerant of losing a copy. Missense variants: 226 observed, 259.48 expected, observed/expected ratio (o/e) 0.87, 90% interval 0.78 to 0.97. Synonymous variants: 87 observed, 96.06 expected, observed/expected ratio (o/e) 0.91, 90% interval 0.76 to 1.08.
Homologues: Orthologues: chimpanzee RHOJ (100% identical), macaque RHOJ (99% identical), pig RHOJ (96% identical), dog RHOJ (96% identical), rabbit RHOJ (95% identical), guinea pig RHOJ (95% identical), rat Rhoj (93% identical), mouse Rhoj (93% identical), tropical clawed frog rhoj (81% identical), zebrafish rhoj (81% identical). Paralogues in human: RHOQ (74% identical), CDC42 (57% identical), RAC3 (55% identical), RAC1 (54% identical), RAC2 (54% identical), RHOU (49% identical), RHOG (48% identical), RHOV (44% identical), RHOB (43% identical), RHOC (43% identical), RHOA (43% identical), RHOF (42% identical), and 10 more.
Diseases named in the same sentence as RHOJ in open-access papers:
RHOJ is named in the same sentence as 35 diseases in open-access papers, as found by Europe PMC text mining. Sharing a sentence is not in itself a finding about the gene and the disease. The quoted sentences say what the papers report.
melanoma (13 papers, 2014 to 2024). A malignant, usually aggressive tumor composed of atypical, neoplastic melanocytes. "Altogether, this suggests that targeting the RHOJ–PAK axis would be beneficial for melanoma patients with BRAF mutations." (PMID 34503171, 2021). "At 1 and 3 days, we also observed a significant up-regulation of RhoJ, which has been associated with melanoma invasion and chemoresistance (Fig2)." (PMID 25538140, 2014). "Recent studies indicate that the RhoJ regulates cell migration and invasion through altering actin cytoskeletal dynamics in malignant melanoma." (PMID 38247865, 2024). "RHOJ, a known regulator of melanoma, breast cancer, and gastric cancer progression, activates signaling cascades in endothelial cells that are required for tumor angiogenesis and induces PAK signaling in tumor cells to promote growth." (PMID 35385746, 2022). "Initially, we selected 68 promising compounds and experimentally tested their half maximal inhibitory concentrations (IC50s) in SKMel28 melanoma cells—a cell line that we previously determined was sensitive to RHOJ depletion." (PMID 35385746, 2022). "Xenotransplantation of lung carcinoma and melanoma cells in RhoJ knockout mice and a spontaneous breast tumor mouse model displayed that RhoJ deficiency causes a double attack on tumor blood vessels." (PMID 35173528, 2022). "Mechanistically, expression of RHOJ in melanoma promotes PAK activation, which favors BAD phosphorylation and cell survival." (PMID 34503171, 2021). "For example, RhoJ is overexpressed in metastatic melanoma and treatment of melanoma cell lines with cisplatin was found to promote PAK1 autophosphorylation in a RhoJ-dependent manner." (PMID 32309283, 2020). "Taken together, these studies indicate that RHOJ is expressed in about half of stage III and stage IV melanoma tumors harboring BRAFV600E mutation." (PMID 28753606, 2017). "Our previously published studies showed that RhoJ regulates PAK activity in human melanoma cell lines." (PMID 28753606, 2017). "As up to 50% of BRAF mutant human melanomas express high levels of RhoJ, these studies nominate the RhoJ-BAD signaling network as a therapeutic vulnerability for fledgling BRAF mutant human tumors." (PMID 28753606, 2017). "Our tissue microarray studies determine that RhoJ is more highly expressed in stage III disease as compared to stage IV disease, suggesting that RhoJ is likely a better therapeutic target in early stage melanomas." (PMID 28753606, 2017). "Taken together, these results identify PAK inhibitors as agents that can block the progression of early stage, BRAF mutant, RhoJ expressing melanomas by modulating BAD signaling." (PMID 28753606, 2017). "Melanoma tumors from RhoJ KO mice metastasized to the lung at a lower rate as compared to RhoJ wild type (WT) mice (p = 0.003, Student’s t-test), suggesting that RhoJ regulates tumor progression, metastasis, or both." (PMID 28753606, 2017). "We previously used a genome-wide RNAi approach to identify RhoJ, a Cdc42 family GTPase, as a gene that allows melanoma cells to resist DNA damage stress in vitro." (PMID 28753606, 2017). "Short-term treatment of nascent melanoma tumors with PAK inhibitors that block RhoJ signaling halts the growth of BRAF mutant melanoma tumors in vivo and induces apoptosis in melanoma cells in vitro via a BAD-dependent mechanism." (PMID 28753606, 2017). "To verify that RhoJ plays a role in the growth of human melanomas, we optimized a RHOJ Ab for immunohistochemistry and examined the expression of RHOJ in AJCC stage III and stage IV melanoma tumors using two well-annotated melanoma tissue FFPE microarrays." (PMID 28753606, 2017). "Approximately half of all human BRAF mutant melanoma tumors express high levels of RhoJ, identifying the RhoJ-BAD pathway as a novel target for melanoma." (PMID 28753606, 2017).
melanoma (continued). "Integration of the Cancer Genome Atlas (TCGA) melanoma RNA-sequencing and exome-sequencing datasets confirmed a higher expression of RHOJ in BRAFV600E as compared to BRAFWT melanoma tissues." (PMID 28753606, 2017). "RhoJ deletion does affect the growth of melanoma tumors, the formation of nevi, and has subtle effects on melanocyte differentiation or development." (PMID 28753606, 2017). "We examined the expression of RhoJ in a panel of human melanoma cell lines and determined that RhoJ expression levels varied widely in BRAFV600E and BRAFWT cells lines." (PMID 28753606, 2017). "Stage III melanoma tumors expressed significantly higher levels of RHOJ than stage IV melanoma tumors." (PMID 28753606, 2017). "RhoJ KO mice developed early stage tumors (as measured by pigmented area) a week later than RhoJ WT tumors, indicating that RhoJ promotes the growth of developing melanoma tumors." (PMID 28753606, 2017). "While nothing is known about the role of RHOQ and RHOU in melanomagenesis, RHOJ participates to chemoresistance through DNA repair control and modulates metastasis potential in melanoma." (PMID 26098773, 2015). "For instance, RHOJ mediates melanoma cell resistance to dacarbazine, RAC1 is involved in breast cancer cell response to trastuzumab and RHOE/RND3 enhances multidrug resistance in gastric cancer cells." (PMID 26098773, 2015). "In melanoma cell lines, it was discovered that not only did RhoJ affect their motility and invasion, but that it also modulated chemoresistance by affecting DNA damage sensing." (PMID 24928894, 2014). "Recently, a role for RhoJ has been identified in regulating the motility and invasion of melanoma cells, suggesting a role for RhoJ in the metastatic spread of malignant melanoma." (PMID 24928894, 2014). "RHOJ regulates chemoresistance, invasion, and tumor angiogenesis in melanoma." (PMID 35385746, 2022). "The observation that RhoJ modulates the expression of complex I components but does not affect tumor angiogenesis in our model identifies RhoJ signaling as a novel regulator of metabolic adaptation in BRAF mutant melanoma cells." (PMID 28753606, 2017). "Targeting RhoJ signaling with existing PAK inhibitors was more efficient at blocking the progression of BRAF mutant tumors in vivo when compared to kinase inhibitors currently used to treat melanoma." (PMID 28753606, 2017). "Additional studies sought to determine whether RhoJ signaling was activated in melanoma cells that express high levels of RhoJ." (PMID 28753606, 2017). "To determine whether blocking RhoJ signaling would be an effective method to inhibit the growth of melanoma tumors, we first examined whether blocking RhoJ signaling pharmacologically was sufficient to induce apoptosis in vitro." (PMID 28753606, 2017). "Future studies will involve assembling tissue collections of early stage melanomas to verify whether RhoJ is an ideal therapeutic target for early stage disease and determine whether RhoJ inhibition blocks both tumor growth and metastasis." (PMID 28753606, 2017). "In addition to modulating DNA damage stress, RhoJ modulates actin cytoskeletal dynamics in melanoma cells, and can regulate tumor angiogenesis in lung cancer xenografts." (PMID 28753606, 2017). "Moreover, 27% of all tumors examined in a human melanoma tissue microarray had both the BRAFV600E mutation and expressed high levels of RHOJ." (PMID 28753606, 2017). "The observation that RhoJ is not mutated in melanoma but yet plays a more important role in the growth of BRAF mutant cells ranging from nevi to tumors indicate that RhoJ is part of a normal signaling pathway that is co-opted to speed tumor development." (PMID 28753606, 2017). "Intriguingly, while RhoJ modulates multiple pathways that may be involved in melanoma growth, it is not mutated in melanoma tumors, suggesting that it may represent a “non-oncogene” dependence in tumor cells." (PMID 28753606, 2017).
melanoma (continued). "RhoJ activates group I p21-activating kinases (PAK) in melanoma cells and PAK inhibitors can sensitize melanoma cells to DNA damage." (PMID 28753606, 2017). "Our initial studies demonstrated that RhoJ deletion slows the initiation and progression of BRAF mutant melanoma tumors in vivo." (PMID 28753606, 2017). "Our observations indicate that although RhoJ is a global KO, its deletion has no detectable effect on the angiogenesis of autochthonous melanomas." (PMID 28753606, 2017). "We reveal that RhoJ modulates the growth properties and apoptotic threshold of BRAF mutant melanocytes, accelerating both the formation of nevi and the growth and metastasis of melanoma tumors." (PMID 28753606, 2017). "CD271 knockdown was found to eliminate the capacity of melanoma cells to form heterogeneous tumors most likely through the downregulation of mediators for melanoma invasion and metastasis (GLI-2, SOX2 and ERBB3), angiogenesis (IGFBP-2), proliferation (FST and MITF) or chemoresistance (RHOJ)." (PMID 25351876, 2015). "While RHOJ and CDC42 have not been found to be mutated in melanoma, they are often overexpressed." (PMID 35385746, 2022). "To validate whether the RhoJ-PAK signaling network influenced the growth of BRAF mutant tumors, we determined whether PAK inhibitors could block the growth of BRAF mutant autochthonous mouse melanomas during early phases of development." (PMID 28753606, 2017). "Interestingly one recent report showed that the CDC42 homologue RhoJ and its effector PAK1 modulate ATR activity via degradation of claspin after DNA damage thereby uncoupling ATR from Chk1; moreover RhoJ appears to be upregulated in advanced melanoma." (PMID 24416382, 2014). "We utilized a Cdc42-PAK functional assay to better evaluate the activation of this family of GTPases in melanoma and determined that RhoJ, Cdc42, and Rac1/2/3 interact with PAK in melanoma cells when they are GTP-bound but not when they are loaded with GDP." (PMID 28753606, 2017).
breast carcinoma (9 papers, 2020 to 2024). "Kaplan–Meier analysis revealed that high RhoJ expression was associated with poorer survival in breast cancer patients." (PMID 32984327, 2020). "Together, these data suggest that RhoJ expression is intimately associated with breast cancer malignancy in vitro and in vivo." (PMID 32984327, 2020). "We investigated the involvement of a Rho GTPase (RhoJ) in breast cancer metastasis focusing on the mechanism underlying RhoJ trans-activation by pro-metastatic cues." (PMID 32984327, 2020). "By using a dual approach with in vitro cell culture and an in vivo mouse model of obesity, we identified the Rho GTPase RhoJ as a major candidate driving breast cancer in an obesity environment." (PMID 38247865, 2024). "MKL-1 mediates TGF-β-induced RhoJ transcription to promote breast cancer cell migration and invasion." (PMID 36494481, 2022). "For example, TGF-β function is mediated by MKL1 in breast cancer, which induces RhoJ transcription to promote cancer cell invasion." (PMID 34761735, 2022). "RHOJ expression is upregulated in breast cancer cells by the prometastatic stimulus TGF-β, which is mediated by MKL1." (PMID 34249916, 2021). "In the present study, we delineate a novel pathway wherein MKL1 recruits the histone H3K9/H3K27 demethylase JHDM1D/KDM7A to regulate breast cancer metastasis through epigenetically activating RHOJ transcription." (PMID 34249916, 2021). "The small GTPase RHOJ is a key regulator of breast cancer metastasis by promoting cell migration and invasion." (PMID 34249916, 2021). "We have previously reported that MKL1 mediates RHOJ trans-activation by TGF-β in breast cancer cells." (PMID 34249916, 2021). "Further analysis confirmed that the H3K9/H3K27 dual demethylase JHDM1D/KDM7A was essential for TGF-β-induced RHOJ transcription in breast cancer cells." (PMID 34249916, 2021). "Of note, there was a significant correlation between MKL1 and RhoJ expression levels in human breast cancer tissues." (PMID 32984327, 2020). "RhoJ depletion attenuated breast cancer cell migration and invasion in vitro and metastasis in vivo." (PMID 32984327, 2020). "We report that expression of RhoJ was up-regulated in malignant breast cancer cells compared to more benign ones." (PMID 32984327, 2020). "Here we report that MKL1 interacts with ERG1 to activate RhoJ transcription and promote breast cancer metastasis." (PMID 32984327, 2020). "In summary, we provide evidence to implicate the ERG1-MKL1 axis in RhoJ trans-activation and breast cancer metastasis." (PMID 32984327, 2020). "In the present study we delineate a novel pathway wherein MKL1 regulates breast cancer metastasis through activating RhoJ transcription." (PMID 32984327, 2020). "Next, two different animal models were exploited to evaluate the effect of RhoJ knockdown on breast cancer cell migration/invasion in vivo." (PMID 32984327, 2020). "Higher RhoJ expression was also detected in human breast cancer biopsy specimens of advanced stages." (PMID 32984327, 2020). "Out of 19 different Rho GTPases tested, RhoJ expression showed the most significant correlation with breast cancer cell malignancy." (PMID 32984327, 2020). "Despite the uncovering of a new transcriptional complex (MKL1-ERG1) that mediates RhoJ transcription in breast cancer cells, major limitations dampen the translational impact of our study." (PMID 32984327, 2020). "To define a broad role for RhoJ in breast cancer metastasis, we then examined the expression levels of different Rho GTPases in different breast cancer cell lines." (PMID 32984327, 2020). "Combined, these data suggest that an ERG1-MKL1 complex activates RhoJ transcription in breast cancer cells." (PMID 32984327, 2020). "In addition, expression data extracted from the public cancer database (TCGA) showed a highly correlative relationship between KDM7A expression and RHOJ expression in human breast cancer tissues." (PMID 34249916, 2021).
breast carcinoma (continued). "KDM7A expression level, either singularly or in combination with that of RHOJ, could be used to predict prognosis in breast cancer patients." (PMID 34249916, 2021). "Both MKL1 and KDM7A seemed to be essential for RHOJ trans-activation in breast cancer cells raising the possibility that MKL1 might interact with and recruit KDM7A to the RHOJ promoter." (PMID 34249916, 2021). "It remains obscure how RhoJ expression is modulated during breast cancer metastasis." (PMID 32984327, 2020). "In addition, we observed in patients with advanced stages of breast cancer elevated RhoJ mRNA expression compared to patients with a less malignant phenotype." (PMID 32984327, 2020). "RhoJ expression was progressively up-regulated, at both mRNA and protein levels, as normal mammary epithelial cells transitioned to breast cancer cells." (PMID 32984327, 2020). "Together, these data suggest that MKL1 might contribute to breast cancer cell migration/invasion by modulating RhoJ expression." (PMID 32984327, 2020). "We next evaluated the effect of RhoJ on breast cancer cell migration and invasion." (PMID 32984327, 2020). "RhoJ silencing again significantly suppressed the metastatic abilities of breast cancer cells." (PMID 32984327, 2020). "We proposed that JHDM1D/KDM7A could participate in RHOJ induction by TGF-β in breast cancer cells." (PMID 34249916, 2021). "For this purpose, we investigated CCL7, CCR5, RhoJ, and MMP9 expression in different breast cancer cells: MCF7, MDA-MB-231, MDA-MB-361, ZR751, BT549, and TD47D by using HME1 as a control." (PMID 38247865, 2024). "We have previously reported that expression of RHOJ, a small GTPase belonging to the RHO family, correlates with worsened prognosis in breast cancer patients." (PMID 34249916, 2021). "Although we show here that KDM7A is potentially important for the malignant spread of breast cancer cells, this observation is unlikely to be easily explained by its activation of RHOJ transcription." (PMID 34249916, 2021). "Third, we examined the effect of RhoJ expression on over-all survival, but not metastasis-free survival, for breast cancer patients." (PMID 32984327, 2020). "We first compared the levels of RhoJ among normal mammary epithelial cells (MCF-10A) and breast cancer cells of varying malignancies (three with strong metastatic capability, MDA-231, MDA-468, and Hs578T, and two with lesser aggressive behavior, MCF-7 and T47D)." (PMID 32984327, 2020). "Together, these data suggest that aggressive behavior of breast cancer cells might be, at least in part, attributable to MKL1-mediated RhoJ trans-activation." (PMID 32984327, 2020).
glioblastoma (5 papers, 2009 to 2024). The most malignant astrocytic tumor (WHO grade IV). "RhoJ (TC10-Like, TCL), a member of Rho GTPase Cdc42 subfamily, facilitates angiogenesis in glioblastoma via JNK/VEGFR2 mediated activation of PAK-BRAF-ERK signaling pathways." (PMID 38953895, 2024).